TLR9 (toll like receptor 9)
Diseases named in the same sentence as TLR9 in open-access papers (continued):
Sharing a sentence is not in itself a finding about the gene and the disease.
cancer (continued). "Activation of the signaling pathways that provide the DNA damage response, as well as activation of TLR9—NF-kB- signaling, contributes to the survival of the cancer cell." (PMID 31205871, 2019). "NET-released high mobility group box 1 (HMGB1) augments cancer cell adhesion, proliferation, and migratory capabilities in vitro in a toll-like receptor 9 (TLR9)-dependent manner." (PMID 30200242, 2018). "The detection of higher frequencies of the TLR2, TLR4 and/or TLR9 polymorphisms in CRC patients compared with the control groups highlight the role of these polymorphism in CRC development and cancer progression." (PMID 29883450, 2018). "Because of multiple immunomodulatory effects, the TLR9 pathway has received increasing attention for the development of cancer therapeutic strategies." (PMID 28241765, 2017). "CpG oligodeoxynucleotides (CpG ODNs), TLR9 agonists, are able to induce anticancer immune responses and exert direct effects against cancer cells, serving as cancer therapeutic agents." (PMID 28241765, 2017). "As mentioned, CpG has shown encouraging clinical efficacy in cancer treatment by activating the immunostimulatory TLR9 pathway." (PMID 29133898, 2017). "Endogenous DNA is recognized by TLR9, and the TLR9-NF-κB pathway has an important function in cancer cell proliferation." (PMID 28574818, 2017). "We have previously shown that TLR9 expression is downregulated in several viral induced cancers including HPV16-induced cervical neoplasia." (PMID 27454079, 2016). "Although there are evidences that demonstrate specifically that TLR9 is altered in cancer cells, proving their role in carcinogenesis remains changeling." (PMID 27454079, 2016). "The TLR9 agonist CpG DNA has been widely used as a cancer vaccine adjuvant or an intra-tumoral mono-therapeutic agent." (PMID 27384490, 2016). "Our data highlight a central role for TLR9 in cancer development, therapeutic strategies to reactive its expression should be targeted." (PMID 27454079, 2016). "Using several different in vitro readout systems, we compare the functions of two TLR9 agonists in clinical development for cancer therapy, dSLIM® and ProMune®, differing in sequence, chemical composition, and structure." (PMID 27980779, 2016). "In recent years, TLR9 has become an attractive therapeutic target for immune modulation in immune diseases, as well as cancer." (PMID 27388672, 2016). "ProMune® and dSLIM® belong to different families of TLR9 agonists and both have been established as cancer immunotherapeutics in clinical proof‐of‐concept studies." (PMID 27980779, 2016). "Our above findings demonstrate that TLR9 expression alone decreases cancer cell proliferation and colony formation as well as inhibit the events that promote transformation." (PMID 27454079, 2016). "TLR9 agonists such as CpG ODN enhance antitumor T-cell responses when used as an adjuvant for anti-cancer therapy." (PMID 25971982, 2015). "Further in vitro functional study verified that silence of TLR9 inhibited migration and invasion of PC-3 cells, indicating expression of TLR9 involving in the migration and invasion of cancer cells." (PMID 26087186, 2015). "Previous in vitro studies suggested that TLR9 activity promotes cancer cell proliferation and/or invasiveness." (PMID 26046794, 2015). "The toll-like receptor 9 (TLR9) agonists CpG oligodeoxynucleotides (CpG ODNs) have been recognized as promising adjuvants for vaccines against infectious diseases and cancer." (PMID 26215533, 2015). "A TLR9 agonist enhanced antitumor T-cell responses when used as an adjuvant for anti-cancer therapy." (PMID 25971982, 2015). "Hypoxia has been shown to induce invasion in various types of cancer cells and, therefore, the involvement of TLR9 in the process of invasion was investigated." (PMID 24959259, 2014). "It has been well established that in addition to the cells of the immune system, TLR9 is frequently expressed in various cancer cell lines, as well as in clinical cancer specimens." (PMID 24959259, 2014).
cancer (continued). "It has been demonstrated recently that viral oncoproteins down-regulate TLR9 expression in various cancer tissues." (PMID 25101078, 2014). "Later, it has been demonstrated that TLR-9 agonists can exert antitumor activity by direct action on cancer cells." (PMID 28548068, 2014). "Based on this preclinical evidence, a large series of clinical studies has been conducted to verify the relevance of TLR-9 agonists for cancer patients’ treatment." (PMID 28548068, 2014). "The activation of the TLR-9 pathway by using synthetic agonists was thought to be a useful mechanism for the elicitation of the host reaction against cancer." (PMID 28548068, 2014). "The rationale that prompted research investigating the possible adoption of TLR-9 agonists in cancer therapy initially relied on their ability to stimulate an inflammatory-like response in order to activate the immune system." (PMID 28548068, 2014). "Promising results were provided by the combination of TLR-9 agonists and cancer vaccines, although coming from very early and small studies, thus requiring confirmation in larger settings." (PMID 28548068, 2014). "The potential use of the immunostimulatory properties of TLR agonists, particularly TLR2, TLR3, TLR4, TLR7/8, and TLR9, has been investigated in cancer immunotherapy." (PMID 25309546, 2014). "Several synthetic CpG oligonucleotides (ODNs) have been developed as TLR-9 agonists with the aim of enhancing cancer immune surveillance." (PMID 28548068, 2014). "A wide series of early clinical studies explored the potential for different TLR-9 agonists as adjuvants for cancer vaccines." (PMID 28548068, 2014). "Several TLR ligands, including imiquimod (TLR7) and CpG (TLR9), have shown significant promise for the treatment of cancer." (PMID 25231413, 2014). "Overall, these observations suggest that, although hypoxia appears to regulate TLR9 expression in various cancer cells, the effects of TLR9 inhibition on hypoxia-induced invasion are specific to cancer type." (PMID 24959259, 2014). "To assess the effect of three selected SNPs (rs352140, rs5743836 and rs187084) in TLR9 on cancer, we performed a meta-analysis based on 11 case-control studies, including a total of 6,585 cancer cases and 7,506 controls." (PMID 23990988, 2013). "The possible pathophysiological significance of cellular DNA receptor TLR9 in various types of cancer has attracted research interest, after studies have established that it is widely expressed in malignant tumor cells." (PMID 23761830, 2013). "It is well established that in addition to being expressed in the immune system, TLR9 is widely expressed in various cancer cell lines and in clinical cancer specimens, including breast, brain, gastric, lung, esophageal, prostate and renal cancer." (PMID 23761830, 2013). "Previous studies have demonstrated that treatment of TLR9-expressing cancer cells with synthetic TLR9 ligands, which mimic the structure of bacterial DNA, stimulates their invasion in vitro through matrix metalloproteinase-13 (MMP-13) activation." (PMID 23761830, 2013). "Toll-like receptor-9 (TLR9) is an intracellular DNA receptor that is widely expressed in breast and other cancers." (PMID 24273604, 2013). "It has been recently shown that TLR9 stimulation with agonistic CpG sequences stimulates invasion in various cancer cells via MYD88-independent and TRAF6 partially dependent pathways." (PMID 24459426, 2013). "Growing studies have revealed the association between polymorphisms in the Toll-like receptor 9 (TLR9) and susceptibility to cancer, however, the results remained inconsistent." (PMID 23990988, 2013). "Locally injected immunostimulatory oligodeoxynucleotides containing CpG motifs (CpG-ODNs), which are TLR9 agonists, have shown promise in cancer models." (PMID 23561041, 2013). "Targeting TLR9 with CpG ODN has been extensively studied for the treatment of cancer and various infectious diseases." (PMID 23151919, 2012).
cancer (continued). "More important, stimulation of the toll-like receptor 9 (TLR9), which mimics bacterial infection, substantially increased the secretion of IgM in human epithelial cancer cells." (PMID 23251529, 2012). "Expression of TLR9 has been previously detected in various cancer cell lines and in various clinical cancer specimens." (PMID 21929816, 2011). "Although the role of TLR9 in the development of these cancers is not fully understood, TLR9 appears to be playing an important modulatory role in several of these tumors." (PMID 20981241, 2010). "Based on these findings, several TLR9 agonists, including CpG oligonucleotides, are currently in development for the treatment of cancer." (PMID 20981241, 2010). "TLR9 resides in the endoplasmic reticulum and its activation results in increased production of inflammatory mediators, Except plasmacytoid DC and B cells, TLR9 can also expressed in breast, gastric, lung and prostate cancer cells." (PMID 20696081, 2010). "Engaging these diverse mechanisms, TLR9 agonists have been found to be therapeutically effective in various cancer trials." (PMID 20981241, 2010). "Oligodeoxynucleotides (ODN) with unmethylated deoxycytidyl-deoxyguanosine (CpG) dinucleotides (CpG ODN) mimic the immunostimulatory activity of bacterial DNA recognised by the Toll-like receptor 9 (TLR9) and are potent adjuvants utilised in cancer therapy." (PMID 16892041, 2006). "In conclusion, we showed in a selection of samples that human malignant tumors express functionally active TLR9 and respond to CpG treatment with prolonged survival and chemokine release." (PMID 15631627, 2005). "CpG-oligonucleotides (CpG-ODN), which induce signaling through Toll-like receptor 9 (TLR9), are currently under investigation as adjuvants in therapy against infections and cancer." (PMID 15631627, 2005). "The receptor for advanced glycation end products (RAGE) promotes nucleic acid uptake through the endosomes where TLR9 is located, enhancing TLR9-dependent responses and activating the NF-κB transcription factors crucial for immune modulation in cancer and chronic inflammation." (PMID 40016346, 2025). "However, aberrant hypomethylation of host DNA (such as in cancer cells or mitochondrial DNA) can similarly lead to TLR9 activation, blurring the line between PAMP and DAMP." (PMID 40981069, 2025). "Notably, mitophagy has also been found to interact with TLR9 to promote the production of the chemokine CXCL10 by cancer cells, which further promotes T-cell recruitment and thus enhances the efficacy of immunotherapy." (PMID 40002724, 2025). "CpG ODN could be recognized by TLR9 to activate humoral and cellular immunity for preventing or treating cancer as one of the most effective immune stimulant adjuvants." (PMID 40855408, 2025). "TLR9 is a DNA receptor that can recognize mammalian DNA containing unmethylated cytosine–guanosine (CpG) dinucleotides and plays a key role in mediating DNA effects on cancer cells." (PMID 40278372, 2025). "Moreover, conjugation of Toll‐like receptor 9 (TLR9) ligands, such as CpG oligonucleotides, with the STAT3‐binding motif enabled selective targeting of TLR9+ immune and cancer cells." (PMID 40227962, 2025). "Although there is some evidence that TLR-9 may be involved in the occurrence and development of cancer, the precise role of this receptor in disease remains unclear." (PMID 39201739, 2024). "Toll-like receptor 9 (TLR9) is a DNA recognizing receptor expressed also in several cancers." (PMID 39644451, 2024). "Moreover, researchers have shown that TLR9 agonists are also highly effective and beneficial when combined with traditional cancer treatment (i.e., radiotherapy or chemotherapy)." (PMID 38685971, 2024). "Using a tailored strategy based on the patient’s TLR9 genotype could potentially make TLR9 agonist therapy in cancer more effective in the future." (PMID 38850110, 2024).
cancer (continued). "Oligodeoxynucleotides (ODNs) containing unmethylated cytosine–phosphate–guanosine (CpG) motifs are readily recognized by Toll-like receptor 9 on immune cells, trigger an immunomodulatory cascade, induce a Th1 -biased immune milieu, and have great potential as an adjuvant in cancer vaccines." (PMID 38932378, 2024). "In this regard, myeloid NF-κB2 could be efficiently knocked down in cancer patients by NF-κB2 siRNAs conjugated with the Toll-like receptor 9 (TLR9) agonists CpG oligonucleotides." (PMID 38385745, 2024). "TLR9 agonist CpG ODN has been recognized as a promising adjuvant for cancer vaccines." (PMID 38537697, 2024). "HPV regulates TLR9 expression in other cancers, such as cervical, and head and neck cancers." (PMID 39644451, 2024). "Like TLR4, there is division surrounding the role of TLR9 activation in cancer pathogenesis." (PMID 38201300, 2024). "Synthetic ligands targeting TLR9, mimicking the structure of bacterial DNA, have been shown to induce cancer cell invasion in vitro, suggesting a potential link between TLR9 activation and cancer progression." (PMID 39123407, 2024). "CpG ODNs are readily recognized by TLR9 on immune cells and trigger an immunomodulatory cascade that involves antigen-presenting cells, T cells, and natural killer cells, which makes them promising for cancer immunotherapy." (PMID 38932378, 2024). "TLR7/8 and TLR9 agonists have been successfully used in cancer treatment." (PMID 36911674, 2023). "In cases where EBV persists in the gastric mucosa and continuously activates TLR-9, the sustained inflammatory response may contribute to transforming normal gastric epithelial cells into cancer cells." (PMID 37894471, 2023). "Thus, the study findings suggest a novel strategy of utilizing the PS-inducing function of TLR9 agonists to develop combinational cancer treatments using PS-targeting drugs." (PMID 37324949, 2023). "Designing interventions that harness TLR-9 activation to enhance immune responses against EBV-infected cancer cells could revolutionize GC treatment strategies." (PMID 37894471, 2023). "Moreover, in vitro stimulation of oral cell lines with a TLR9 agonist, up-regulates the secretion of molecules involved in cancer cell invasion." (PMID 35990685, 2022). "Given this, we hypothesised that TLR1, TLR2, TLR3, TLR7, TLR8, and TLR9 would be involved in a negative regulatory mechanism mediated by TLR8-AS1 that contributes to the maintenance of cancer stem cell features." (PMID 35801728, 2022). "On the other hand, TLR9 may also be involved in cancer development, as various reports demonstrated that TLR9 activity is associated with enhanced malignancy, and it impacts assorted immune activities against cancer." (PMID 35239059, 2022). "Cytosine–phosphate–guanine (CpG) oligodeoxynucleotides are common immune adjuvants in cancer therapy, and act as Toll-like receptor 9 (TLR9) agonists to trigger T helper 1 (Th1) cell-mediated immune activation, involving maturation, proliferation, and differentiation of various type of immune cells." (PMID 36587223, 2022). "Inhibitor of MAPK pathway using mitogen-activated protein kinase (MEK) inhibitor in combination with chemotherapy triggers mitophagy of cancer cells, which induces the release of mitochondrial DNA that interact with Toll Like receptor 9 (TLR9) to promote the production of the chemokine CXCL10." (PMID 35529902, 2022). "However, it is worth mentioning that TLR7 and TLR9 expression levels were negatively linked with cancer cell sensitivity to Irofulven, an alkylating agent, indicating that as TLR7 and TLR9 expression levels grew, the risk of Irofulven resistance increased." (PMID 35801728, 2022). "TLR9 immunotherapy is gaining traction for use in treating infectious diseases as well as cancers." (PMID 35865810, 2022). "Here, we have concentrated on the function of TLR4, TLR7, and TLR9 in the cancer in this section." (PMID 35801728, 2022).
cancer (continued). "Therefore, further studies are needed to clarify the role of TLR-9 in preventing HPV infection or promoting cancer development." (PMID 36428532, 2022). "The function of TLR9 in cancer development has been particularly well studied." (PMID 39871923, 2022). "Moreover, TLR-9 agonists were employed as potent adjuvants of cancer vaccines against various types of cancers." (PMID 34202080, 2021). "TLR4 and TLR9 could also orchestrate a signal that helps cancer cells to bypass the immune responses by increasing the expression of immunosuppressive cytokines and anti‐apoptosis proteins." (PMID 33336901, 2021). "Furthermore, TLR9 agonists were shown to shift M2 Mφs to the M1 type, which, in accordance, can enhance an efficient immune response against cancer cells." (PMID 34202080, 2021). "Although cancer and cancer stem cells express a high level of TLR9, whether a decrease of STAT3 can occur via reduction of TLR9-mediated signaling by CQ application was not investigated in this paper." (PMID 34299065, 2021). "So, scientists should consider the oncogene role of TLR4 and TLR9 in cancer cells." (PMID 32380783, 2020). "The stimulation of multiple innate immunity signaling pathways may greatly improve the efficacy of cancer vaccines over that achieved by TLR9 signaling alone." (PMID 31980914, 2020). "Many drugs targeting TLR-9 and other TLRs are under clinical trials, mainly for cancer therapy." (PMID 32934605, 2020). "Since TLR polymorphisms have been associated with changes in susceptibility to many diseases, including cancers and TLRs promote the survival of cancer cells, we also correlated the coexistence of previously genotyped TLR (TLR2, TLR4 and TLR9) polymorphisms with the VDR polymorphisms." (PMID 32471257, 2020). "TLR9 likely promotes stemness in cancer cells via MYD88 and STAT3." (PMID 32843056, 2020). "However, NETs can trigger HMGB1 (High mobility group box 1) release, activating TLR9-dependent pathways in cancer cells, thereby promoting tumor cell adhesion, proliferation, migration, and invasion after surgical stress." (PMID 31477121, 2019). "TLR9 is an endosomal receptor frequently upregulated in many cancer types, including HCC." (PMID 30894684, 2019). "The results in this report therefore support the potential utility of the TLR7/8 ligands CL097 and CL075, the TLR7 ligand IMQ, and the TLR9 agonists CpG A, B, and C, in the treatment of cancer or other diseases in which the activation of pDCs may be desirable." (PMID 31093508, 2019). "TLR9 agonists combined with anti-PD-1 antibodies show synergistic anti-cancer effects." (PMID 30400835, 2018). "In our study, both TLR9 T1237C and T1486C polymorphisms were more frequent in CRC patients compared to the control groups, and especially in stage IV patients, indicating their role in cancer development and progression." (PMID 29883450, 2018). "As a novel toll-like receptor 9 (TLR9) agonist, synthetic unmethylated cytosine-phosphate-guanine (CpG) oligodeoxynucleotides can stimulate a Th1 immune response and potentially be used as therapeutic agents or vaccine adjuvants for the treatment of cancer." (PMID 30120629, 2018). "TLR9 was also shown to be overexpressed in high-grade cervical lesions and/or cancer." (PMID 29854832, 2018). "As a result, deepening the understanding of the oncogenic mechanisms in B-cell malignancies will enable matching treatments with the cancer genotype, thus providing further possibilities for the therapeutic manipulation of TLR9 as a target for the precise treatment of B-cell malignancies." (PMID 28241765, 2017). "Furthermore, the TLR9 expression in malignant B cells is heterogeneous in each cancer subtype, even in individual patients." (PMID 28241765, 2017). "Furthermore HMGB1-dependent activation of TLR9 pathways was found to occur in cancer cells upon exposure to NETs and to increase proliferation, invasion and migration." (PMID 28166238, 2017).